CD34 (CD34 molecule)
Diseases named in the same sentence as CD34 in open-access papers (continued):
Sharing a sentence is not in itself a finding about the gene and the disease.
leukemia (continued). "CD34+CD38– is the most widely used CSC marker in leukemia, whereas CD133+ was described as the first brain CSC marker." (PMID 33763422, 2021). "Relative to PBMC, BMHealthy, and quiescent CD34+, intact basal respiration was elevated in primary leukemia, as well as CD34+GFs, reminiscent of that seen in AML cell lines and entirely consistent with their proliferative phenotypes." (PMID 34132194, 2021). "Multiple studies have shown that leukemia stem cells (LSCs) in AML immunophenotypically resemble committed progenitor cells such as lymphoid-primed multi-potent progenitors (LMPPs) (Lin-CD34+CD38-CD90-CD45RA+) or GMPs (CD34+CD38+CD123+/loCD110-CD45RA+)." (PMID 35822030, 2021). "Designing multiplex bead assays specifically for the phenotyping of leukemia-derived EVs including antigens such as CD34 and CD123, as well as frequently expressed aberrant markers, would allow the establishment of comprehensive phenotypic profiles." (PMID 35008226, 2021). "As a proof of concept, we demonstrate that a small-molecule inhibitor rationally designed against MBNL1 can preferentially kill MLL-rearranged leukemia cells while sparing normal CD34+ hematopoietic stem/progenitor cells." (PMID 32398749, 2020). "When we further isolated primary CD34+ cells from MLL leukemia patient cells and inhibited their LAMP5-AS1 expression, we found that LAMP5-AS1 knockdown promoted the level of differentiation in leukemia stem and progenitor cells." (PMID 32552847, 2020). "In human leukemia-derived cell lines and CD34+ hematopoietic progenitor cells, CXCL14 can compete with CXCL12 and thus inhibit CXCL12-CXCR4 signaling." (PMID 32708730, 2020). "Knowledge of adult stem cells and progenitor cells catalyzed the adoption of cell surface markers to characterize CSCs, for example, CD44+CD24lowLin− for breast CSC, and CD34+CD38− for leukemia stem cells." (PMID 32953979, 2020). "We further found that LAMP5-AS1 suppression significantly impaired the capacity of primary cells from MLL leukemia patients to form colonies in methylcellulose, which was in parallel with the reduced proportion of CD34+ leukemia cells." (PMID 32552847, 2020). "Increased numbers of studies have shown that other than hematopoietic stem cells, many other types of cells also express CD34 molecules, such as certain types of leukemia cells, solid tumor cells, vascular endothelial cells, and fibroblasts." (PMID 32974176, 2020). "In our model, further experiments using different subgroups expressing CD34 or CD38 are needed to determine the metabolic dependency of methionine in MLLr leukemia-initiating cells." (PMID 32456310, 2020). "LAMP5-AS1 suppression significantly reduced colony formation and increased differentiation of primary MLL leukemia CD34+ cells." (PMID 32552847, 2020). "MCT1 and MCT4 mRNAs are overexpressed in pro-monocytic U937 and promyelocytic NB4 leukemia cell lines, as compared to normal CD34+ HPCs and G and Mo differentiating HPCs." (PMID 33614502, 2020). "For example, purified CD34+CD38− leukemia stem cells regenerated cells with the same markers as well as distinct subpopulations carrying CD34+CD38+ markers." (PMID 32953979, 2020). "In vivo, AXL inhibition resulted in prolonged survival of tumor-bearing mice and reduced the growth of CD34+ leukemia stem cells." (PMID 31694201, 2019). "CD47 cell surface protein expression was increased on CD34+CD38–CD90–Lin– leukemia stem cells (LSCs) compared to normal CD34+CD38–CD90+Lin– hematopoietic stem cell (HSC) counterparts." (PMID 32038992, 2019). "CD-34 positive cells (98%) at day 0, still showed a high level of CD-34 antigen (more than 70%) as stemness marker after 10-day treatment with leukemia microvesicles." (PMID 31548916, 2019). "In conclusion, we demonstrated that DFX treatment is able to influence differentiation processes both in healthy haematopoietic CD34+ stem/progenitor cells and in leukemia cell models, thus suggesting a general mechanism of action." (PMID 31196186, 2019).
leukemia (continued). "Our data therefore further strengthen the use of GPR56 not only as a marker for LSC activity among bulk leukemia cells in CD34‐positive AML at diagnosis but also as a promising prognostic marker." (PMID 30848055, 2019). "In fact, this has been demonstrated by clinical trials using magnetic bead-based, FDA-approved CliniMACS and ISOLEX 300i CD34 + cell isolation systems for treatment of leukemia and other hematologic diseases." (PMID 30659223, 2019). "We propose that personalized, autologous transplantation can be developed for certain blood-related diseases, such as leukemia, using normal CD34+ cells isolated from a small volume of mPB after efficient ex vivo expansion in HEM." (PMID 31196160, 2019). "HHT and ATO synergistically reduce cell viability in leukemia stem-like cells and CD34+ primary cells." (PMID 31307525, 2019). "By transfer in immunocompromised mice, they identified a leukemia stem cell that was almost exclusively CD34+; CD38−." (PMID 31083587, 2019). "With this graft manipulation, the infused mononuclear cells also contain, in addition to HSC (including not only CD34+ but also CD34− precursors), effector cells such as mature (CD56dim) NK cells and TCRγδ T cells, both capable of anti-leukemia activity." (PMID 32010130, 2019). "The similar extent of engraftment and development of leukemias in (hCB)-CD34+ NSG and controls suggests a poor human immune response against not compatible hAMLs." (PMID 31536492, 2019). "In the majority of AML patients, the CD34+/CD38− fraction contains cells with the potential of leukemia initiating cells." (PMID 30813354, 2019). "In agreement with many previous studies, we found lower CD34 expression on leukemia cells from patients with NPMmut." (PMID 31185600, 2019). "In fact, also various TCA cycle-related genes were higher expressed in leukemias compared to normal CD34+ cells, and the same was seen for some glutaminolysis-related genes." (PMID 31890203, 2019). "This suggests that H3K27me3 HIST1high marks a more mature leukemia independently of the level of CD34 expression." (PMID 31606046, 2019). "CD34+CD38− cells can initiate leukemia efficiently, but CD34−CD38+ cells cannot, showing the existence of leukemia stem cells." (PMID 30310855, 2018). "The leukaemia blasts often co-express haematopoietic progenitor markers (CD34), B lymphoid markers (CD19, CD22, CD79a, Tdt), myeloid markers (CD15, CD65) and components of the leukocyte antigen complex (HLA-DR)." (PMID 28819864, 2018). "Next, miR-375 notably decreased the number of colonies in leukemic cell lines and reduced colony formation in 5 of 6 CD34+ leukemia stem/progenitor cells from AML patients." (PMID 29439669, 2018). "Accumulating evidence shows that CD34+CD38- leukemia stem cells (LSCs) are responsible for drug resistance, metastasis, and relapse of leukemia." (PMID 30013477, 2018). "Studies further detected the expression of CD34 in isolated cancer stem cells of leukemia, colorectal cancer, brain tumors, and head and neck cancer, which indicates a potential of CD34 as a surface marker of tumor stem cells." (PMID 30046596, 2018). "In this study, we found that Nanog, a transcription factor in stem cells, is significantly overexpressed in CD34+ populations from patients with acute myeloid leukemia and in LSCs from leukemia cell lines." (PMID 30013477, 2018). "Our results showed that the CD25-negative population of Lin–CD34+CD38– or Lin–CD34+ cells from CD25-positive AML patients reconstituted leukemia at the primary or secondary transplantation in the absence of the CD25-positive population." (PMID 30550585, 2018). "Next, marker enrichment modeling (MEM) was used to characterize feature enrichment in comparison to a population of CD34+CD38−Lin− cells within the leukemia sample." (PMID 29295987, 2018).
leukemia (continued). "The majority of AML samples express cell surface CD34, and most studies of LSCs have focused on the CD34+CD38− cell compartment, which has been associated with leukemia initiation and relapse." (PMID 29466292, 2018). "IGF1R mRNA expression showed a highly significant (P < 0.0001) positive correlation with Nanog mRNA expression in CD34+ leukemia cells." (PMID 30013477, 2018). "The combination of donor and ZFNs demonstrated here is able to truncate BCR-ABL oncoprotein efficiently in CML cells and CML CD34+ cells and show the anti-leukemia ability in vitro and in vivo." (PMID 29554925, 2018). "qPCR analysis demonstrated that Nanog mRNA levels were significantly higher in CD34+ leukemia cells than in CD34- counterparts, and overexpressed in LSCs (CD34+CD38-)." (PMID 30013477, 2018). "Here, we report the in vitro and in vivo activity of DS in combination with copper (Cu) against CD34+/CD38+ leukemia stem-like cells sorted from KG1α and Kasumi-1 AML cell lines, as well as primary CD34+ AML samples." (PMID 28518151, 2017). "First, we examined the cytotoxic effect of DS/Cu on CD34+/CD38− leukemia stem-like cells sorted from KG1α cells by MTT assay." (PMID 28518151, 2017). "CD34, which is well established marker of hematopoietic and leukemia stem cells, was detectable only in the first responder cluster." (PMID 28422713, 2017). "Using the difference in ALDH activity in combination with detection of aberrant leukemia-associated marker expression, CD34+CD38− HSCs and CD34+CD38− LSCs from AML bone marrows have been purified." (PMID 28665351, 2017). "Both articles evaluated the expression of CD82 in the self-renewing leukemia stem cell (LSC) compartments (CD34+/CD38− cells) and the CD34+/CD38+ compartments of AML cells." (PMID 28646224, 2017). "The leukemia cells under study all originate from adult bone marrow stem or progenitor cells, thus we consider the marrow CD34+ cells to be biologically closest to the studied leukemias and thus optimal control cells." (PMID 28301528, 2017). "Simultaneously, our previous works further confirm the tumor suppressor function of chidamide in CD34+ human leukemia stem cells while it spared CD34+ normal hematopoietic cells." (PMID 28814980, 2017). "Our data proved that the survival leukemia cells from chemotherapies presented much higher level of CD34+, indicating that there are a higher proportion of stem / progenitor cells in these residual population cells." (PMID 28114350, 2017). "In these observations, the frequency (population fraction) of those non-SCs with the phenotype switching potential has been found to be lower than that of the original CD34+ CD38- leukemia-initiating cells." (PMID 29084232, 2017). "Initial reports described a specific cell surface phenotype for LSCs that allowed primitive leukemia cells to be distinguished from normal stem and progenitor cells (CD34+, CD38-, CD123+ and so on)." (PMID 28114350, 2017). "Last, to assess in vivo antitumor effects of DS/Cu, CD34+/CD38− KG1α cells were grafted in mice to a leukemia mouse model as described in detail in Methods." (PMID 28518151, 2017). "Hh signaling pathway is active in primary CD34+ LSCs and cytokine-responsive CD34+ cell lines (Kasumi-1, Kasumi-3 and TF-1) and contributes to the survival and drug resistance of CD34+ leukemia stem cells." (PMID 28137265, 2017). "UCB derived CD34+ cells have been already used for the autologous transplantation in the treatment of childhood leukemia." (PMID 28415626, 2017). "In this vein, overexpression of TAL1s stimulates the transcription of β-hemoglobin in human leukemia K562 cells and promotes erythroid differentiation of human cord blood CD34+ cells cultured in erythropoietin-containing medium." (PMID 28545085, 2017).
leukemia (continued). "Significantly lower expression has been demonstrated for CD34+/CD38− leukemia-initiating cells (LICs) vs. AML bulk cells, but expression was still significantly higher compared to their healthy counterparts (CD34+/CD38− normal hematopoietic stem cells)." (PMID 28743264, 2017). "Activity of this pathway correlated with leukemia progression and therapy resistance and increase of eIF2α-P in primary Lin-CD34+ cells accompanied CML progression and enhanced their leukemogenic potential." (PMID 27802179, 2016). "Ara-C treatment significantly reduced total numbers of leukemia cells, including CD34+ positive cells, which was partially alleviated by the addition of FGF2." (PMID 27481339, 2016). "Xenograft transplantation studies have demonstrated a rare population of leukemia-initiating cells called leukemic stem cells (LSCs) capable of propagating leukemia that are enriched in the CD34+/CD38− fraction." (PMID 27465508, 2016). "In bone marrow, FGF2 treatment increased total numbers of leukemia cells, including CD34+ positive leukemia cells." (PMID 27481339, 2016). "K562 represents CML blast crisis, consisting of primitive blast-like leukemic cells, while the CD34+CD38− population of KG1a demonstrated the leukemia stem-like cell property in vivo." (PMID 27110755, 2016). "Ara-C treatment significantly reduced total numbers of leukemia cells and CD34+ positive leukemia cells, which was partially alleviated by the addition of FGF2." (PMID 27481339, 2016). "Certain diagnoses were clearly over-represented in this group of samples, including splenic B-cell lymphoma, null cell lymphoma and CD34-positive leukaemia." (PMID 27863542, 2016). "In contrast, the traditional chemotherapy drug Ara-C exhibited little apoptosis when tested against total primary leukemia cells abf CD34+CD38- cells at concentrations of 5 and 10 μM." (PMID 27658462, 2016). "For T-ALL3 case, cells isolated from primary mice re-initiated leukemia with a slight delay for CD7+/CD34− cells compared to CD7+/CD34+ cells in secondary recipient." (PMID 27191650, 2016). "The idea to identify CSCs by flow cytometry comes from leukaemia where LSCs constitute a population of CD34+CD38- cells capable of generating leukaemia in immunosupressed mice." (PMID 27766946, 2016). "On sorting, the CD34+/CD99+ and CD34-/CD99+ subpopulations represented the majority of leukemia blasts (31.5±43% and 62.2±44%, respectively), while the CD34+/CD99- subpopulation was the smallest (0.40±0.7%)." (PMID 27764235, 2016). "Three subsets of LKS+ HSCs, namely, LT-HSCs (LKS+CD34− or LKS+CD150+CD48−), ST-HSCs (LKS+CD34+Flk2−) and MPPs (LKS+CD34+Flk2+), all suffered progressive decreases in absolute numbers during leukemia development." (PMID 27585558, 2016). "In BM, FGF2 treatment increased total numbers of leukemia cells including the number of CD34+ positive leukemia cells." (PMID 27481339, 2016). "In T-ALL3 case, the majority of CD7+/CD34+/− derived-cells isolated from BM of primary mice are CD34− and re-initiate leukemia in secondary recipient only with a slight delay for CD7+/CD34− cells compared to CD7+/CD34+ cells." (PMID 27191650, 2016). "Although LSCs were initially described as Lin- CD34+ CD38lo/, it is well-established that cells with leukemia initiating ability and stem-ness properties exist outside of the Lin- CD34+ CD38lo/- population." (PMID 27074138, 2016). "As expected, T-ALL6 cells derived from primary recipient re-initiated leukemia in secondary faster than primary transplant with a slight delay for CD7+/CD34− cells compared to CD7+/CD34+ cells." (PMID 27191650, 2016). "Normal CD34+CD38– cells showed relatively less apoptotic response to alantolactone treatment comparing with the response to leukemia stem cells at 10 μM." (PMID 27658462, 2016).
leukemia (continued). "In a large cohort of 2028 children with ALL, the treatment outcomes of a subset of B-lineage ALL patients with CD10+CD19+CD34+ immature B-progenitor leukemia were compared with the treatment outcomes of the remaining CD19+ B-lineage ALL patients." (PMID 28018598, 2016). "These comprised two splenic B-cell lymphomas, four lymphoma NOS samples, two null-cell lymphomas, and three CD34-positive leukaemias." (PMID 27863542, 2016). "These pre-LSC are fundamentally distinct from the tumor initiating, CD34+ CD38− leukemia stem cells (LSC or leukemia-initiating cells, LIC) described extensively over the past two decades." (PMID 27597933, 2016). "In those cases, CD7+/CD34+/− cell fractions gave rise to genetically and phenotypically different leukemia in NSG mice." (PMID 27191650, 2016). "Here, we identified the role of miR-150 in proliferation and tumorigenicity in leukemia stem cells (LSCs; CD34+CD38- cells)." (PMID 27917123, 2016). "Several studies also suggest that leukemia hematopoietic stem cells (CD34+) are sensitive to fatty acid oxidation inhibition with etomoxir." (PMID 26350211, 2016). "We observed that CD7+/CD34+/− cell fractions from the T-ALL we studied endowed with fast promoting leukemia activity are homogenous in terms of genetics and migration/niche adhesion abilities." (PMID 27191650, 2016). "Data were compared to transcriptomes of various other human leukemia models we had generated over the years, including CB CD34+ cells transduced with MLL-AF9, FLT3-ITD, NUP98-HOXA9, STAT5A and KRASG12V." (PMID 27055152, 2016). "NK cells (derived from donor's CD34+ precursors) that express KIRs, mismatched with their HLA ligands in the donor versus recipient direction, clear leukemia blasts residual after the conditioning regimen, thus preventing leukemia relapses." (PMID 27563819, 2016). "In this study, 9-color panels, including CD10, CD19, CD20, CD22, CD34, CD79a, CD179a, and IgM, which are sequentially expressed during B cell development, were designed to detect the leukemia cell subpopulations in adult B-ALL patients." (PMID 27559941, 2016). "We observed that CD7+/CD34+ or CD7+/CD34− T-ALL cells that promote leukemia within a short-time period are genetically similar, as well as xenograft-derived leukemia resulting from both cell fractions." (PMID 27191650, 2016). "The antibody decreased proliferation of the primary T-ALL cells and depleted leukemia initiating CD34/CD44 high population." (PMID 26046801, 2015). "Along the same line, CD34+ and CD34− cells have the same leukemia initiation potential in infant MLL gene rearranged ALL." (PMID 26236346, 2015). "These miRs are expressed in mobilized CD34+HSCs and/or in leukaemia 41,42 and are reported to act as tumour suppressors 43,44." (PMID 26082201, 2015). "This study showed that treatment with CD82 mAb increased the population of human CD34+ leukemia cells circulating in the PB in vivo." (PMID 26139471, 2015). "During the differentiation of leukemia cells, CD34 is expressed in AML malignant cells, while the expression P-gp is decreased." (PMID 25435954, 2015). "Others possess a finite capacity to replicate and eventually differentiate into immature leukemia cells, which account for the majority of malignant cells; these express the CD34 in the AML subgroup cells." (PMID 25435954, 2015). "Exposure of AML cells to CD82 mAb inhibited the survival of AML cells in vitro (data not shown), excluding the possibility that the treatment with CD82 mAb stimulated the proliferation of CD34+ leukemia cells in vivo." (PMID 26139471, 2015). "Low levels of CD45 and CD34 were occasionally detected, either due to leukemia cell or monocyte (CD45 or CD34) or endothelial cell (CD34) contamination." (PMID 25860293, 2015). "This is in agreement with previous data on CD34+ leukemia cell lines, such as KG1, showing high expression of DNMT3B." (PMID 25948775, 2015).